EGFR (epidermal growth factor receptor)
Diseases named in the same sentence as EGFR in open-access papers (continued):
Sharing a sentence is not in itself a finding about the gene and the disease.
head and neck squamous cell carcinoma (continued). "In the transplanted tumor model of head and neck squamous cell carcinoma (HNSCC), EGFR was negatively correlated with the expression of the autophagy marker LC3B, indicating that EGFR signaling is involved in the regulation of autophagy function." (PMID 33055358, 2020). "Head and neck squamous cell carcinoma (HNSCC) patients frequently develop treatment resistance to cetuximab, a monoclonal antibody against EGFR, as well as radiotherapy." (PMID 32424150, 2020). "The anti-epidermal growth factor receptor (EGFR) antibody cetuximab is standard therapy for head and neck squamous cell carcinoma (HNSCC)." (PMID 31570699, 2019). "Epidermal growth factor receptor (EGFR) plays an important role in head and neck squamous cell carcinoma (HNSCC) proliferation and therapy resistance, but the efficacy of targeting of EGFR for therapy has been limited." (PMID 30585254, 2019). "Anti-CD147 therapy led to synergy in combination with inhibition of EGFR and reduced head and neck squamous cell carcinoma (HNSCC) cell proliferation and migration." (PMID 31744072, 2019). "As a proof of concept, the anti-EGFR antibody cetuximab has been shown to improve radiation sensitivity in head and neck squamous cell carcinoma (HNSCC) in multicenter phase III clinical trials." (PMID 30621219, 2019). "Alterations in the epidermal growth factor receptor (EGFR) is one of the major events in head and neck squamous cell carcinoma (HNSCC), being overexpressed in up to 90% of patients." (PMID 28881811, 2017). "The most prominent example is the combination of radiotherapy with cetuximab, an inhibitory antibody directed against the epidermal growth factor receptor (EGFR) which is used to treat patients with head and neck squamous cell carcinoma (HNSCC;)." (PMID 29340031, 2017). "Another report provided evidence that the growth of head and neck squamous cell carcinomas (HNSCC) were reduced in PDX mice by dual targeting of EGFR and ErbB3." (PMID 28417948, 2017). "Cetuximab, the most commonly used anti-EGFR antibody, has received considerable attention and achieved encouraging progress for the treatment of head and neck squamous cell carcinoma(HNSCC)." (PMID 27974693, 2017). "In NSCLC and head and neck squamous cell carcinoma (HNSCC) for example, EGFR signaling and downstream MEK/ERK activation induces expression of AXL mRNA via the JUN transcription factor." (PMID 28251492, 2017). "In head and neck squamous cell carcinoma (HNSCC), the role of Endothelial Growth Factor Receptor (EGFR) in cancer progression has been extensively investigated." (PMID 28841839, 2017). "Furthermore, radiotherapy reportedly increased numbers of EGFR-positive CTCs in locally advanced head and neck squamous cell carcinomas (HNSCC), which could be counteracted upon treatment with anti-EGFR antibody Cetuximab." (PMID 27683128, 2017). "Head and neck squamous cell carcinoma (HNSCC) is known to be intrinsically resistant to inhibitors for epidermal growth factor receptor (EGFR)." (PMID 28134774, 2017). "The median overall survival for recurrent or metastatic head and neck squamous cell carcinoma (HNSCC) remains less than one year despite a wide armamentarium of therapeutic approaches including anti-EGFR antibody Cetuximab." (PMID 26575422, 2016). "Epidermal growth factor (EGF) receptor (EGFR) gene is frequently amplified inhead and neck squamous cell carcinoma (HNSCC)." (PMID 27510965, 2016). "Clinical treatment options for KRAS wild-type EGFR in head and neck squamous cell carcinoma (HNSCC) and metastatic colorectal cancer (mCRC), encompass monoclonal antibodies (mAbs) cetuximab and panitumumab." (PMID 27602494, 2016). "Cetuximab (C225), an anti-EGFR monoclonal humanized antibody interacting with the extracellular binding site of EGFR to block ligand stimulation, serves as a targeted therapy approved for the treatment of head and neck squamous cell carcinoma (HNSCC)." (PMID 27313893, 2016).
head and neck squamous cell carcinoma (continued). "Overexpression of epidermal growth factor (EGF) and EGF receptor (EGFR) is also noted in head and neck squamous cell carcinoma (HNSCC)." (PMID 26919242, 2016). "For head and neck squamous cell carcinomas (HNSCC) the only approved molecular targeting approach in combination with X-irradiation (IR) is the targeting of the epidermal growth factor receptor (EGFR) using the antibody cetuximab." (PMID 27281611, 2016). "The epidermal growth factor receptor (EGFR) has been implicated in OSCC carcinogenesis and is overexpressed in up to 90% of head and neck squamous cell carcinoma (HNSCC)." (PMID 25918252, 2015). "Among the RTKs, the epidermal growth factor receptor (EGFR) has emerged as an independent prognostic factor for several cancers, including head and neck squamous cell carcinoma (HNSCC), and an appealing target for therapeutic intervention 6,7." (PMID 25355701, 2015). "Further, EGFR inhibitors or blockade of the EGFR protein with selective monoclonal antibodies sensitized cancer cells to radiation therapy by blocking the repair of damaged DNA and improved clinical outcomes in a subset of patients with head and neck squamous cell carcinoma." (PMID 26546517, 2015). "Anti-EGFR (epidermal growth factor receptor) antibody based treatment strategies have been successfully implemented in head and neck squamous cell carcinoma (HNSCC)." (PMID 26120042, 2015). "Furthermore, Brand and colleagues demonstrated that AXL is involved in acquired resistance to cetuximab in models of head and neck squamous cell carcinoma (HNSCC), in which it was overexpressed, activated and tightly associated with EGFR expression in cancer cells resistant to cetuximab." (PMID 25966280, 2015). "Targeting therapy to the epidermal growth factor receptor (EGFR) is a new and effective treatment for head and neck squamous cell carcinoma (HNSCC)." (PMID 26538233, 2015). "In a meta-analysis of phase II studies of EGFR TKIs in head and neck squamous cell carcinoma (HNSCC), diarrhoea occurred in 45% of patients." (PMID 25126444, 2014). "Overexpression and EGFR phosphorylation are frequently detected in several cancers, such as head and neck squamous cell carcinoma (HNSCC), and lung, breast, prostate, ovary, and bladder cancers." (PMID 23383347, 2013). "As a matter of fact, research on the development of prognostic and predictive markers in head and neck squamous cell carcinomas (HNSCC) has led to the incorporation of cetuximab, an anti-EGFR monoclonal antibody, into the contemporary therapeutic management." (PMID 23360534, 2013). "For example, overexpression of EGFR, which occurred in 90% of head and neck squamous cell carcinoma (HNSCC), predicted an inferior patient outcome." (PMID 22427815, 2012). "Only a minority of cancer patients benefits from the combination of EGFR-inhibition and radiotherapy in head and neck squamous cell carcinoma (HNSCC)." (PMID 23046567, 2012). "Cetuximab, an immunoglobulin-G1 antibody against EGFR, and erlotinib, a small-molecule inhibitor of the intracellular tyrosine kinase domain of EGFR, are among the novel targeted therapeutic agents to result in improved survival in patients with head and neck squamous cell carcinoma." (PMID 21917153, 2011). "For example, EGFR is frequently over-expressed in Head and Neck Squamous Cell Carcinoma (HNSCC) and is correlated with poor disease-free survival and overall survival in these patients." (PMID 21908901, 2011). "The key deregulated signaling pathways in head and neck squamous cell carcinoma (HNSCC) include EGFR, Ras, TGFβ, NFκB, Stat, Wnt/β-catenin and PI3-K/AKT/mTOR." (PMID 19284526, 2009). "In our previous study, we demonstrated that targeting three epithelial-related markers, EpCAM, epidermal growth factor receptor (EGFR), and MET, increased the CTC detection rate in patients with head and neck squamous-cell carcinoma (HNSCC)." (PMID 40699639, 2025).
head and neck squamous cell carcinoma (continued). "In head and neck squamous cell carcinoma (HNSCC), studies found that the combination of the epidermal growth factor receptor (EGFR) inhibitor cetuximab and the PARP-1 inhibitor olaparib produces significant synergistic radiosensitizing effects." (PMID 41367875, 2025). "In head and neck squamous cell carcinoma spheroids, CAFs increased tumor proliferation and EMT via epidermal growth factor receptor (EGFR) expression." (PMID 41050078, 2025). "The humanized bsAb targeting EGFR and HER3 duligotuzumab has demonstrated tumor growth inhibition in preclinical models of NSCLC and HNSCC (head and neck squamous cell carcinoma) resistant to erlotinib and cetuximab." (PMID 40243603, 2025). "Herein, we compared the molecular profiles and clinical significance of CTCs based on the expression of epithelial-related markers (EPCAM, EGFR, and MET) in patients with head and neck squamous-cell carcinoma (HNSCC)." (PMID 40699639, 2025). "The epidermal growth factor receptor (EGFR) is a cell surface receptor found mainly in cells of epithelial origin and present in up to 90% of head and neck squamous cell carcinoma (HNSCC) biopsies." (PMID 39858084, 2025). "Similarly, in head and neck squamous cell carcinoma (HNSCC), CAFs promote resistance to EGFR inhibitors through the secretion of Matrix Metalloproteinases (MMPs) and Amphiregulin (AREG)-mediated receptor stabilization." (PMID 40940809, 2025). "In this work, we showed that head and neck squamous cell carcinoma (HNSCC) cells exposed to cetuximab, monoclonal antibody targeting EGFR, can modulate EGFR expression of MVs." (PMID 40766966, 2025). "In another, a positive feedback loop involving EGFR/Akt/mTORC1 and IKK/NF-κB was shown to influence proliferation in head and neck squamous cell carcinoma." (PMID 41144548, 2025). "The efficacy of anti‐PD‐1 and EGFR therapies for head and neck squamous cell carcinoma (HNSCC) can be predicted using various markers; however, the stability of these markers remains unclear." (PMID 40156197, 2025). "In a phase I/II clinical trial, epidermal growth factor receptor (EGFR)-targeted NIR-PIT was found to be safe and effective against unresectable or recurrent head and neck squamous cell carcinoma." (PMID 38555315, 2024). "For example, the downstream signaling pathways of epidermal growth factor receptor (EGFR), such as Akt or ERK, were aberrantly activated, promoting tumor cell proliferation and leading to EGFR-TKI afatinib resistance in head and neck squamous cell carcinoma." (PMID 39606630, 2024). "A recent study suggested that AXL heterodimerizes with EGFR, thereby activating YAP via the EGFR–LATS1/2 axis, a potential reason for head and neck squamous cell carcinoma (HNSCC)." (PMID 38607003, 2024). "In head and neck squamous cell carcinoma (HNSCC), CTTN induces gefitinib resistance by attenuating EGFR and c-MET degradation." (PMID 36831511, 2023). "For example, targeting EGFR with erlotinib (Tarceva, Genentech) induces vascular normalization by reducing the expression of hypoxia-inducible factor-1α (HIF-1α) and VEGF in head and neck squamous cell carcinoma (HNSCC) xenograft models." (PMID 37907742, 2023). "The combination of monalizumab and cetuximab (anti-EGFR) potentiates the NK cells and LTCD8 ADCC in vitro, and showed safety and potency for disease control in preclinical models and in patients with head and neck squamous-cell carcinoma (SCCHN)." (PMID 35203609, 2022). "Epidermal growth factor receptor (EGFR) is both a driver oncogene and a therapeutic target in advanced head and neck squamous cell carcinoma (HNSCC)." (PMID 36076232, 2022).
head and neck squamous cell carcinoma (continued). "Epidermal growth factor receptor (EGFR) inhibitors are approved by the Food and Drug Administration (FDA) for the treatment of several cancers including head and neck squamous cell carcinoma (HNSCC)." (PMID 35158773, 2022). "Another study discovered significant differences in the expression of EGFR/PI3K/Akt/mTOR signaling-related proteins and clinical prognosis in patients with HPV16-positive or HPV16-negative head and neck squamous cell carcinoma (HNSCC)." (PMID 36249021, 2022). "EGFR was upregulated in the CTC fraction in breast xenograft model and head and neck squamous cell carcinoma patients with locally advanced disease, EGFR promoted TNBC cell clustering and blockade of EGFR successfully abolished tumor cell cluster formation." (PMID 35725558, 2022). "For example, an epidermal growth factor receptor (EGFR) inhibitor, cetuximab, which is approved by the FDA, suppresses the expression of HIF-1α and sensitizes head and neck squamous cell carcinoma (HNSCC) cells to radiotherapy." (PMID 34200019, 2021). "In head and neck squamous cell carcinoma, HOXB5 plays an oncogenic role through the EGFR/Akt/Wnt/b-catenin signaling axis." (PMID 34440097, 2021). "While genetic alterations in Epidermal growth factor receptor (EGFR) and PI3K are common in head and neck squamous cell carcinomas (HNSCC), their impact on oncogenic signaling and cancer drug sensitivities remains elusive." (PMID 34178665, 2021). "Cancer stem-like cells of head and neck squamous cell carcinoma (HNSCC) that survive treatment with cetuximab, an epidermal growth factor receptor (EGFR)-targeting agent, are sensitive to the induction of ferroptosis by SSZ." (PMID 33401672, 2021). "The EGFR gene is frequently amplified in head and neck squamous cell carcinoma (HNSCC)." (PMID 33804548, 2021). "Several studies have examined the correlation between EGF receptor (EGFR) expression and tumour stage in patients with head and neck squamous cell carcinoma (HNSCC), all concluding that the expression of EGFR is heterogeneous and that the expression of this receptor is independent from tumour stage." (PMID 34115785, 2021). "Several signaling pathways are aberrantly activated in head and neck squamous cell carcinoma (HNSCC), including the Hedgehog-Gli (HH-GLI), WNT, EGFR, and NOTCH pathways." (PMID 32899202, 2020). "It was reported that PS1 activated the epidermal growth factor receptor (EGFR)–signal transducers and activators of transcription (STAT) pathway to inhibit apoptosis in head and neck squamous cell carcinoma." (PMID 32587587, 2020). "These efforts may further include other cancers that exhibit resistance to EGFR-directed therapies, like head and neck squamous cell carcinoma (HNSCC)." (PMID 30863492, 2019). "EGFR activation in head and neck squamous cell carcinoma (HNSCC) through overexpression and autocrine/paracrine mechanisms is frequent and antibody-based EGFR inhibitors such as cetuximab are approved therapeutics that provide benefit." (PMID 29458371, 2018). "EGFR phosphosites p.Y1068 and p.Y1173 are active in GBM, head and neck squamous cell carcinoma (HNSC), KIRC, LUAD, and LUSC." (PMID 30053901, 2018). "However, therapies targeting wild-type EGFR in tumors such as head and neck squamous cell carcinoma (HNSCC) have been less effective due to intrinsic and acquired tumor resistance to EGFR inhibitors." (PMID 29268862, 2017). "Dacomitinib is an irreversible tyrosine kinase inhibitor targeting EGFR, HER2 and HER4 with antitumor activity demonstrated pre-clinically in EGFR wild type and mutant LADC models, as well as clinically in head and neck squamous cell carcinoma and LADC." (PMID 29156674, 2017).
head and neck squamous cell carcinoma (continued). "Moreover, head and neck squamous cell carcinoma (HNSCC) exhibits high levels of EGFR expression with comparable tumor biology to ESCC." (PMID 28038457, 2017). "We hypothesized that Chk1/2 inhibition (CHKi) with prexasertib may enhance cytotoxicity from EGFR inhibition plus radiotherapy in head and neck squamous cell carcinoma (HNSCC)." (PMID 28138028, 2017). "Similarly, in head and neck squamous cell carcinoma (HNSCC) cells in vitro, D1(A12) suppressed proliferation and motility in the absence or presence of the EGFR tyrosine kinase inhibitor (TKI) gefitinib." (PMID 29230082, 2017). "This is in line with previous findings that anti-EGFR antibodies, including cetuximab, can induce EGFR phosphorylation but fail to trigger downstream signaling in NSCLC and head and neck squamous cell carcinoma cell lines." (PMID 28467975, 2017). "Clinical findings consistent with this idea come from a phase I clinical trial in which head and neck squamous cell carcinoma (HNSCC) patients were undergoing combination treatment with the anti-EGFR antibody cetuximab with increasing doses of the proteasomal inhibitor, bortezomib." (PMID 27612423, 2016). "We used spheroid cultures of head and neck squamous cell carcinoma (HNSCC) cell lines as a model for such CTC clusters for determining the role of the epidermal growth factor receptor (EGFR) in cluster formation ability and cell survival after detachment from the extra-cellular matrix." (PMID 27643613, 2016). "Up to 90% of head and neck squamous cell carcinomas (HNSCC), including OSCC, are known to overexpress EGFR and this leads to excessive activation of the EGFR signaling pathway." (PMID 26497678, 2016). "Cellular immune responses specific to wild-type EGFR have been studied in patients with several types of cancer, including NCSLC and head and neck squamous cell carcinoma (HNSCC)." (PMID 27833557, 2016). "Additive or supra-additive effects have been demonstrated in head and neck squamous cell carcinoma (HNSCC) cell lines concurrently treated with vinorelbine and EGFR TKI." (PMID 27135612, 2016). "In head and neck squamous cell carcinoma, induction of MMP-1 by CAFs protected cells from cetuximab (epidermal growth factor receptor (EGFR)-targeting monoclonal antibody)." (PMID 26690480, 2015). "In head and neck squamous cell carcinoma (HNSCC), expression levels of the epidermal growth factor receptor (EGFR) correlate with poor prognosis and decreased survival rates." (PMID 21970318, 2011). "In head and neck squamous cell carcinoma (HNSCC), the anti-EGFR monoclonal antibody cetuximab has been proven to prolong overall survival in combination with radiotherapy and to enhance response rates in recurrent/metastatic disease in combination with cisplatin or fluorouracil." (PMID 18826647, 2008). "Moreover, the mRNA levels of EGFR and PCBP2 showed a positive correlation across different types of tumors, including head and neck squamous cell carcinoma (HNSCC)." (PMID 39816681, 2025). "Oxytocin has been demonstrated to increase Egr-1 expression via an EGFR- and ERK-dependent pathway in head and neck squamous cell carcinoma, which may inhibit tumor invasion and metastasis by promoting E-cadherin overexpression." (PMID 37046823, 2023). "For example, cetuximab sarotalocan combines an EGFR monoclonal antibody with the light activatable dye, IR700, and in a phase I trial of three patients with recurrent head and neck squamous cell carcinoma, two of three patients experienced a response with a manageable safety profile." (PMID 37631232, 2023).